PDIA3 (protein disulfide isomerase family A member 3)
Diseases named in the same sentence as PDIA3 in open-access papers (continued):
Sharing a sentence is not in itself a finding about the gene and the disease.
ovarian carcinoma (23 papers, 2011 to 2026). A malignant neoplasm originating from the surface ovarian epithelium. "Studies have shown that the silence of PDI can cause cytotoxicity in ovarian cancer cells, illustrating the important role of PDIA3 in the prognosis of OV patients and its potential as a prognostic biomarker." (PMID 35401558, 2022). "The PDIA3 expression is increased in ovarian cancer cells, which is considered as a potential biomarker for the prognosis of ovarian cancer." (PMID 36046686, 2022). "PDIA3 has been shown to confer chemo/radioresistance to various types of tumor cells such as ovarian carcinoma." (PMID 31886273, 2019). "PDIA3 expression level is correlated with the clinical outcome of patients with ovarian carcinoma who receive chemoradiotherapy, and the sensitivity to paclitaxel can be enhanced by PDIA3 silencing." (PMID 31886273, 2019). "A study of a number of different ovarian cancer cell-lines reported PDIA3 mRNA expression to be strongly elevated compared to human ovarian surface epithelial cells, and protein expression followed the same pattern." (PMID 24961659, 2014). "For example, PDIA3 expression is increased in ovarian cancer cells and has been considered as a potential biomarker for ovarian cancer prognosis." (PMID 23782473, 2013). "Furthermore, the outcomes of OS, DSS, PFI, and DSS all showed that PDIA3 was a protective factor for ovarian cancer (OV)." (PMID 35401558, 2022). "Interestingly, PDIA3 has been reported to enhance the ability of cervical and ovarian cancer cells to proliferate and invade, indicating its potential as a sensitive marker for reflecting tumor prognosis during gynecologic oncology." (PMID 33292199, 2020). "Although PDIA3 was found to be over-expressed in YDOV-139 ovarian cancer cell line, in this study, CS-resistant ovarian cancer cell line showed decreased levels of the protein compared to the parent cell line suggesting its involvement in resistance to cisplatin." (PMID 27566066, 2016). "Overexpression of PDIA3 has been reported in various tumors, including melanomas, cervical carcinoma, ovarian carcinoma, esophageal squamous cell carcinoma, and hepatocellular carcinoma, and is associated with tumor progression, metastasis and poor patient survival rate." (PMID 23782473, 2013). "PDIA3 was shown as a potential biomarker in ovarian cancer and prostate cancer." (PMID 22363243, 2011). "It has also been shown that LYAR, PDIA3, NOP14, NCALD, MTSS1 and CYP1B1 are correlated with the prognosis of ovarian cancer." (PMID 34696677, 2021). "Firstly, the expression analyses of patients with ovarian cancer showed that the expression levels of CALR and PDIA3 in ovarian cancer were significantly up-regulated in compared with normal control tissues, while the expression of PANX1, ANXA1, HMGB1, and IFNAR1 were nonsignificant." (PMID 35991556, 2022). "In addition, LYAR and five other genes (PDIA3, NOP14, NCALD, MTSS1, and CYP1B1) showed potential as prognostic biomarkers for radical ovarian cancer." (PMID 34696677, 2021). "A gene expression profile study with whole blood cell mRNA from ovarian cancer patients revealed LYAR and other five genes (PDIA3, NOP14, NCALD, MTSS1 and CYP1B1) as potential prognostic biomarkers for curative and postoperative supportive therapies for ovarian cancer." (PMID 26413750, 2015). "Secondly, the survival analyses of patients with ovarian cancer clearly indicated that the expression levels of CALR, PDIA3, ANXA1, HMGB1, IFNAR1, and PANX1 had no significant influence on overall survival (OS) and disease-free survival (DFS)." (PMID 35991556, 2022).
hepatocellular carcinoma (21 papers, 2007 to 2025). A malignant tumor that arises from hepatocytes. "For example, in hepatocellular carcinoma, PDIA3 expression is associated with increased tumor cell proliferation and decreased apoptosis, and increased expression of PDIA3 indicates poor prognosis." (PMID 38213579, 2023). "For example, in patients with diffuse glioma, clear cell renal cell carcinoma, and hepatocellular carcinoma, high expression of PDIA3 is associated with poor survival outcomes." (PMID 36406049, 2022). "Furthermore, PDIA3 has been implicated in the progression of hepatocellular carcinoma through the modulation of the STAT3 signaling cascade." (PMID 38761176, 2024). "In hepatocellular carcinoma, increased expression of PDIA3 is associated with poor prognosis." (PMID 38213579, 2023). "Moreover, PDIA3 promotes cancer cell proliferation and is associated with poor prognosis in hepatocellular carcinoma, while the helicase HELLS functions in DNA-strand separation and replication repair." (PMID 37208732, 2023). "The expression of PDIA3 is also up-regulated in colon adenocarcinoma, hepatocellular carcinoma, invasive breast carcinoma, and prostate adenocarcinoma." (PMID 38213579, 2023). "In HepG2 (hepatocellular carcinoma) cancer cells, ERp57/PDIA3 undergoes a nuclear translocation after tumor necrosis factor-α treatment." (PMID 35109791, 2022). "Higher expression of PDIA3 associates with poor survival outcomes in patients with multiple cancers, such as in diffuse gliomas, clear cell renal cell carcinoma, and hepatocellular carcinoma (HCC)." (PMID 35401558, 2022). "In human hepatocellular carcinoma, PDIA3 downregulation inhibits cell proliferation and, through STAT3 signaling, induces apoptosis in agreement with the observation that PDIA3 knockdown reduces phosphorylated STAT3 and downstream STAT3-related protein levels." (PMID 34829762, 2021). "The involvement of PDIA3 in cancer progression was previously evaluated in other tumor types (i.e., renal cancer and hepatocellular carcinoma)." (PMID 33153019, 2020). "PDIA3 expression in hepatocellular carcinoma is positively correlated with tumor grade and alpha-fetoprotein (AFP) level." (PMID 23782473, 2013). "Similarly, PDIA3 expression is associated with tumor proliferation and decreases apoptosis in hepatocellular carcinoma, and increased expression of PDIA3 predicts poor prognosis." (PMID 29228584, 2017). "Moreover, another study on hepatocellular carcinoma (HCC), where the increased expression of ERp57/PDIA3 was a marker of poor prognosis, revealed a specific role of ERp57/PDIA3 in association with phosphorylated (pY705) STAT3 on HCC progression." (PMID 35109791, 2022). "Additionally, PDIA3 promotes the invasion and proliferation of acute myeloid leukemia and suppresses the migration and proliferation of keratinocytes—for example, PDIA3 could promote the growth of hepatocellular cancer." (PMID 34950658, 2021).
melanoma (21 papers, 2009 to 2024). A malignant, usually aggressive tumor composed of atypical, neoplastic melanocytes. "The combination of CPI-613 and hydroxychloroquine enhanced the localization of ERp57/PDIA3 to the surface of melanoma cells." (PMID 38434963, 2024). "CPI-613/HCQ treatment leads to metabolic depletion, followed by the relocation or accumulation of ERp57/PDIA3 on the cell surface membrane in melanoma cells." (PMID 38434963, 2024). "We have analyzed the antiproliferative potential of analogs and found that 21(OH)pD inhibits melanoma growth through a mechanism independent from VDR or PDIA3." (PMID 30200275, 2018). "Previously, PDIA3 was demonstrated to interact with specific DNA sequences in both HeLa cells and a melanoma cell line." (PMID 26745629, 2016). "Hyperpigmentation of melanoma cells is also associated with a decrease of the VDR, RXR and PDIA3 mRNA levels in B16-F10 cells." (PMID 25811927, 2015). "PDIA3 is also connected to the apoptotic process and has an anti-apoptotic effect in the melanoma cells after induction of endoplasmatic reticulum stress." (PMID 23782473, 2013). "Recently published data connected PDIA3 to apoptosis and demonstrated an anti-apoptotic effect of PDIA3 in the melanoma cell line A375 after induction of ER stress." (PMID 21614181, 2010). "Recently published data connected PDIA3 to the apoptotic process and demonstrated an anti-apoptotic effect of PDIA3 in the melanoma cell line A375 after induction of ER stress." (PMID 20035634, 2009). "The downregulation of Erp57/PDIA3 inhibited ICT-induced apoptosis in Mewo melanoma cells." (PMID 38434963, 2024). "Therefore, the ICT antibody acts as a tumor suppressor in melanoma cells by targeting the cell membrane ERp57/PDIA3, expression of which was enhanced by the combination of CPI-613 and hydroxychloroquine." (PMID 38434963, 2024). "The heterogeneous results indicated that the PDIA3 was a hazardous prognostic marker in eighteen independent tumor cohorts and a favorable prognostic marker in fifteen independent tumor cohorts including melanoma in regard to OS." (PMID 32687065, 2020). "On the other hand, the expression of VDR and its splicing variants and other vitamin D related genes (RXR, PDIA3, CYP3A4, CYP2R1, CYP27B1, CYP24A1 and CYP11A1) was detected in WM98 and A375 melanomas with the transcript levels being modulated by vitamin D analogs." (PMID 30200275, 2018). "In addition, Western blot analysis demonstrated a negative correlation between 21(OH)pD treatment and the amount of PDIA3 in the nuclear fraction, while nuclear localization of PDIA3 was slightly increased by 1,25(OH)2D3 or by calcipotriol treatment of pigmented B16-F10 melanoma cells." (PMID 25811927, 2015). "CPI-613/HCQ induced the cell surface localization of Erp57/PDIA3 in melanoma cells, and ICT eliminated the cell surface expression of Erp57/PDIA3." (PMID 38434963, 2024). "In conclusion, this study revealed that ICT, an ERp57/PDIA3 antibody, induces apoptosis in melanoma cells treated with CPI-613/HCQ." (PMID 38434963, 2024). "In this study, ICT, an anti-ERp57/PDIA3 antibody, induces apoptosis in melanoma cells treated with CPI-613/HCQ." (PMID 38434963, 2024). "Our group showed a specific interaction of ERp57/PDIA3 with several different DNA sequences in HeLa (cervix adenocarcinoma) and melanoma cell lines." (PMID 35109791, 2022). "We further analyzed the expression level of PDIA3 and response to anti-PD-L1 immunotherapy at urological tumors and anti-PD1 in melanomas." (PMID 35401558, 2022). "The treatment of A375 melanoma with four vitamin D3 analogs (1,25(OH)2D3, calcipotriol and 21(OH)pD) decreased the expression of VDR, RXR, PDIA3, CYP2R1 genes." (PMID 30200275, 2018). "siRNA-mediated downregulation of ERp57/PDIA3 did not significantly induce ICT-mediated apoptosis in melanoma cells in the presence of CPI-613 and hydroxychloroquine." (PMID 38434963, 2024).
melanoma (continued). "We speculate that the localization of ERp57/PDIA3, or other cell surface membrane molecules, the expression of which is chaperoned by ERp57/PDIA3, might be important for rescuing melanoma cells from metabolic depletion-induced apoptosis." (PMID 38434963, 2024). "A search against COSMIC identified a number of mutations found in tumors (i.e. adenocarcinoma, squamous cell carcinoma, malignant melanoma and clear cell renal cell carcinoma) localizing within fragments corresponding to SPATA22, ZBTB17, CCT7, MAP1S and PDIA3 proteins." (PMID 35205757, 2022). "Furthermore, the expression of vitamin D3-related genes was altered by vitamin D3 analogs, and the effects on the expression of VDR, RXR, PDIA3, CYP2R1 or CYP24A1 were stronger in WM98 melanoma cells in comparison to the A375 line." (PMID 30200275, 2018). "PCR fragments characteristic for VDR, CYP27A1 and CYP27B1 mRNAs were below the level of detectability in SK-MEL-188b melanoma, which did not respond to vitamin D. Only the mRNA of PDIA3 was detected in this line." (PMID 30200275, 2018).
cervical carcinoma (16 papers, 2012 to 2023). A carcinoma arising from either the exocervical squamous epithelium or the endocervical glandular epithelium. "Recent studies have shown that PDIA3 regulates cell invasiveness in cervical cancer and that a high level of PDIA3 is associated with a low patient survival rate." (PMID 26745629, 2016). "PDIA3 is also up-regulated in cervical cancer tissues, and elevated expression of PDIA3 is associated with shorter survival of patients, suggesting that PDIA3 can be used as a marker of poor prognosis in cervical cancer." (PMID 38213579, 2023). "However, in our study, PDIA3 was associated with fewer dendritic and B cells, suggesting that it may be involved in immune infiltration of the cervical cancer microenvironment." (PMID 36894874, 2023). "The genomic level changes of PDIA3 were further analyzed through cBioPortal database to study the upstream mechanism of PDIA3 in cervical cancer." (PMID 36406049, 2022). "This study aims to investigate the expression of PDIA3/ERP57 in cervical cancer patients and clinical significance, as well as its impact on the prognosis of patients." (PMID 36406049, 2022). "Further analysis of the relationship between PDIA3 and cervical cancer tumor staging based on the GEPIA2 database suggested that the expression of PDIA3 significantly increased with the progression of tumor staging." (PMID 36406049, 2022). "The high or low expression of PDIA3 was significantly correlated with the clinicopathological classification of cervical cancer patients." (PMID 36406049, 2022). "The positive expression rate of PDIA3 in cervical cancer tissues was higher than that in the adjacent cancer tissues, and the difference was statistically significant (χ2 = 4.7946, P < 0.05)." (PMID 36406049, 2022). "Based on the GEPIA2 database, the expression of PDIA3 in 306 cervical cancer patients in the TCGA and GTEx databases was further verified." (PMID 36406049, 2022). "Based on LinkedOmics database, the Spearman's method was used to analyze the co-expressed genes of PDIA3 in TCGA cervical cancer." (PMID 36406049, 2022). "The expression level of PDIA3 is closely related to the survival and prognosis of cervical cancer patients, DNA methylation, and immune cell infiltration." (PMID 36406049, 2022). "The results showed that the expression level of PDIA3 in cervical cancer tissues was significantly higher than that in normal tissues, which was consistent with the results of TIMER2.0 analysis." (PMID 36406049, 2022). "The chi-squared test or Fisher's exact test was used to analyze the correlation between high or low expression of PDIA3 and clinicopathological factors in patients with cervical cancer." (PMID 36406049, 2022). "This indicates that PDIA3 is highly expressed in cervical cancer and can be used as one of the indicators for poor prognosis of late cervical cancer patients." (PMID 36406049, 2022). "Based on the LinkedOmics database, the differentially co-expressed genes of PDIA3 in cervical cancer were analyzed, and the top5 0 genes with significant difference (P < 0.05) and the closest correlation were screened out to plot the heat map." (PMID 36406049, 2022). "The experimental results showed that the expression level of PDIA3 in cervical cancer tissues was significantly higher than that in adjacent cancer tissues." (PMID 36406049, 2022). "The correlation between PDIA3 expression and the infiltration levels of each immune cell in cervical cancer was evaluated." (PMID 36406049, 2022). "Studies in China and abroad have shown that there are differences in the expression of PDIA3/ERP57 in cervical cancer." (PMID 36406049, 2022). "The results showed that the expression level of PDIA3 in cervical cancer tissue was significantly higher than that in normal tissue, and the difference was statistically significant (P < 0.05)." (PMID 36406049, 2022).
cervical carcinoma (continued). "The relationship between PDIA3 expression level and immune-related cell infiltration level was analyzed for the downstream mechanism of PDIA3 in cervical cancer." (PMID 36406049, 2022). "In another study, PDIA3 expression was found to be negatively correlated with infiltration of B cell memory, T cell regulatory, monocytes, and macrophages M2, but positively correlated with NK cell activated and mast cells activated in cervical cancer." (PMID 38213579, 2023). "In TCGA_CESC, compared with the paracancerous (n = 3), the expression level of PDIA3 in the cervical cancer tissue (n = 304) was significantly increased (P < 0.05 represents a significant difference), and PDIA3 showed strong immunoreactivity in the cervical cancer tissue." (PMID 36406049, 2022). "Therefore, in the future scientific research work, we will carry out in-depth discussion and research on PDIA3 with the view to provide the direction for the diagnosis, treatment, and prognosis of cervical cancer." (PMID 36406049, 2022). "This indicated that the high expression of PDIA3 in cervical cancer might be regulated by methylation modification." (PMID 36406049, 2022). "PDIA3 can be used as a marker of poor prognosis of cervical cancer." (PMID 36406049, 2022). "At present, there are few studies on PDIA3 and cervical cancer, and the role and specific mechanism of PDIA3 in the occurrence and development of cervical cancer remain unclear." (PMID 36406049, 2022). "The results showed that the expression of PDIA3 was negatively correlated with methylation level, indicating that the high expression of PDIA3 in cervical cancer might be regulated by methylation modification." (PMID 36406049, 2022). "The results showed that PDIA3 was significantly overexpressed in 16 TCGA cancers (P < 0.05), and only lowly expressed in thyroid cancer tumor tissues, and it had strong immunoreactivity in cervical cancer tissues." (PMID 36406049, 2022). "The PDIA3 expression in cervical cancer tissues in the TCGA and Genotype-Tissue Expression databases was further verified based on the GEPIA2 database to analyze the relationship between the PDIA3 expression and the pathological stage of cervical cancer patients." (PMID 36406049, 2022). "This indicates that PDIA3 (ERP57) in cervical cancer may regulate the occurrence and development of cervical cancer by regulating related molecules, affecting biosynthesis, and changing the related pathways, such as protein processing." (PMID 36406049, 2022). "In summary, this study has demonstrated that the expression of PDIA3 in cervical cancer is up-regulated, and the high expression of PDIA3 is related to tumor progression, which may be an independent prognostic biomarker of cervical cancer." (PMID 36406049, 2022). "The PDIA3 expression in cervical cancer tissues was significantly higher than that in normal tissues, which (F = 2.74, PR (>F) = 0.0436) was significantly increased with the progression of tumor stage, and PDIA3 showed strong immunoreactivity in cervical cancer tissues." (PMID 36406049, 2022). "As such, PDIA3 was even proposed as a prognostic marker for cervical cancer." (PMID 26745629, 2016). "These genes were uploaded to the GEPIA database, which showed that in cervical cancer and paracancerous tissues, the expression levels of seven genes, CD47, FKBP4, IRF-1, LDHA, PDIA3, TFRC, and SLC16A1, were significantly higher in cancer tissues (p < 0.05) than in healthy tissues." (PMID 36894874, 2023). "There were 67 PDIA3 protein positive expression cases (60.4%) and 44 negative expression cases (39.6%) in 111 cervical cancer tissues." (PMID 36406049, 2022). "Furthermore, the relationship between PDIA3 and cervical cancer tumor staging was analyzed based on the GEPIA2 database, to preliminarily explore the distribution of PDIA3 in cervical cancer tumor staging and draw the violin figure of tumor staging." (PMID 36406049, 2022).
cervical carcinoma (continued). "The high or low expression of PDIA3 in cervical cancer tissues was not significantly correlated with age, recurrence, T stage, and N stage (P > 0.05), but significantly correlated with pathological type (P = 0.0004)." (PMID 36406049, 2022).